NOTCH1 (notch receptor 1)
Diseases named in the same sentence as NOTCH1 in open-access papers (continued):
Sharing a sentence is not in itself a finding about the gene and the disease.
tumor (continued). "Intriguingly, NOTCH1 knockdown inhibited tumor growth, as the tumor size under observation and the wet weight of xenograft tumors formed from cells transfected with both siRNA2010 and siRNA6150 were significantly decreased compared with that of the control." (PMID 25149541, 2014). "The active forms of Notch1, along with other transcription factors, regulate the expression of many tumor promoting genes." (PMID 24899509, 2014). "Athymic nude mice were injected with cells transfected with visfatin or Notch1 siRNA, and tumor formation was measured after 30 days." (PMID 24970818, 2014). "Analysis of miR-34a and NOTCH1 expression in tumor retrieved from animal demonstrated efficient delivery and gene modulation induced by SNALPs miR-34a in the absence of systemic toxicity." (PMID 24587182, 2014). "Pathway analysis suggested that potentially actionable mutations in wild-type tumours, including NF1, KIT and NOTCH1, were spread over various signalling pathways." (PMID 24752294, 2014). "Despite the variation between samples, however, the intensity of nuclear Notch1 expression in each primary tumor and its correlate xenografts was stable reinforcing that Notch1 expression remains consistent across subsequent xenograft generations." (PMID 25072022, 2014). "To assess the importance of NOTCH1 in primary CRC, we compared the level of NOTCH1 expression in 45 paired tumor and adjacent normal tissues." (PMID 24885920, 2014). "We have also evaluated the SNALP miR-34a delivery in tumor tissues and the modulation of its canonic target NOTCH1 (respectively)." (PMID 24587182, 2014). "Other studies had shown that under hypoxic conditions, Notch1 stimulated NSCLC tumor growth through direct upregulation of IGF1-R and survivin, both of which enhanced cell proliferation and survival." (PMID 25477004, 2014). "Mechanistically we demonstrate that the activity of KPT-185 is associated with nuclear retention of Fbw7; which degrades nuclear Notch-1 leading to decreased tumor promoting markers such as C-Myc, Cyclin-D1, Hes1 and VEGF." (PMID 24899509, 2014). "The orally bioavailable SINE (KPT-251) showed potent anti-tumor activity in a Colo-357 PDAC xenografts model; residual tumor analysis showed activation of Fbw7 concomitant with attenuation of Notch1 and its downstream genes." (PMID 24899509, 2014). "The expression levels of Notch1 and Jagged1 were found to statistically correlate with tumor size, grade, TNM stage and disease relapse." (PMID 24959218, 2014). "NOTCH1 which is prominently expressed by epithelial cells of the crypts promotes tumor growth by enhancing the G1-S transition of the cell cycle and by increasing cell migration and invasion under pathological conditions." (PMID 24885920, 2014). "Similar to its expression pattern, NOTCH1 has been shown to either promote or suppress tumor genesis, growth, and metastasis through its regulation of different target genes in a specific tissue environment and cancer microenvironment." (PMID 25149541, 2014). "Meanwhile, expression of Notch-1 was also found to be significantly correlated with histological subtypes (P = 0.021), tumor differentiation (P = 0.05), lymph node metastasis (P = 0.026)." (PMID 24423157, 2013). "Human NOTCH1 can function either as an oncogene or a tumour suppressor depending on the cellular context, which often reflects the physiological role of NOTCH1 in the particular stage or cell type." (PMID 23667323, 2013). "Increasing evidences have shown that Notch-1 is involved in the regulation of tumor cell growth, proliferation, apoptosis, metastasis and chemo- or radioresistance." (PMID 24423157, 2013). "miR-34a was also reported to target Notch signaling pathway to inhibit tumor stem cell invasion by directly binding to NOTCH1, DLL1 and JAG1 as well as Wnt signaling pathway by targeting WNT1 and WNT3 genes and TGF-β signaling pathway via Smad4." (PMID 23823624, 2013).
tumor (continued). "Our study indicated that GCSCs play an important role in tumor angiogenesis, and Notch-1 is one of the most likely mediators involved in this process." (PMID 23710217, 2013). "A total of 136 of 215 patients whose tumor infiltrate depth was T3+T4 had significantly higher incidences of high Notch1 expression than those patients with a tumor infiltrate depth T1+T2 (53.0%) (P = 0.018)." (PMID 24312514, 2013). "The positive Notch-1 protein was predominantly located in the cell membrane and (or) cytoplasmic, especially tumor cells." (PMID 24423157, 2013). "Our findings indicated that GCSCs play an important role in tumor angiogenesis, and Notch-1 is one of the most likely mediators involved in these processes." (PMID 23710217, 2013). "NOTCH1 is a double-edged sword with respect to tumorigenesis, being capable of serving as a tumor suppressor as well as an oncoprotein." (PMID 23825651, 2013). "Genotypic data from humans and experimental results from mice indicate that NOTCH1 also has varied roles in cancer, acting as either an oncogene or a tumor suppressor gene depending on cellular context." (PMID 23825651, 2013). "Given the emerging importance of Notch1 signalling in tumour initiation and progression, our findings provide important evidence for the potential benefits of CK2 inhibitors." (PMID 23651443, 2013). "The overexpression of Notch1 may endorse the tumor cells with higher stemness, more therapy-resistance and strong potential in invasion and metastasis as partly indicated in our study and partly in literature, while functional mutation of Notch1 may play an important role in tumor initiation." (PMID 23409141, 2013). "In mammalian skin, Notch1-mediated signaling exerts a critical pro-differentiation and tumor suppressing function." (PMID 24260356, 2013). "Notch-1 was either reported as an oncogene in some solid tumors, or reported as a tumor suppressor in other tumors." (PMID 24423157, 2013). "Although hypoxia-mediated activation of the Notch1 pathway plays an important role in tumor cell survival and invasiveness, the interaction between HIF-1α and Notch1 has not yet been identified in T-ALL." (PMID 23289374, 2013). "To examine the role of Notch in tumor angiogenesis, we have used the Notch1 decoy (N1D), a soluble construct derived from the extracellular domain of the Notch1 receptor that blocks Notch activation by sequestering Notch ligands." (PMID 24066611, 2013). "For example, in epidermis, Notch1 is a tumour suppressor gene that represses the Wnt/β-catenin pathway, while Wnt signalling is known to promote epidermis neoplasia." (PMID 22615875, 2012). "We investigated a role for Notch1 in the tumor environment by orthotopically injecting KPC tumor cells directly into the pancreas of a mouse in which Notch1 had been deleted in all epithelial cells." (PMID 23284900, 2012). "Compared to non-tumor tissues, Notch1 and Jagged1 expression was significantly elevated both in mRNA and protein levels in tumors." (PMID 22506064, 2012). "Our studies using doxycycline to suppress NOTCH1 activity in tumor-bearing mice suggest that NOTCH1 inhibition prevents or, at a minimum, delays disease recurrence." (PMID 22992387, 2012). "As a first step to prove this concept, in this communication we report the in vitro and in vivo therapeutic effects of H101/Notch1-siRNA combined therapy in HeLa-S3 tumor cells." (PMID 23071601, 2012). "At this stage, animals began to receive an intra-tumor injection of Notch1-siRNA, H101 or PBS every three days, for a total of four injections." (PMID 23071601, 2012). "In this study, we tested a new strategy of tumor gene therapy by combining a Notch1-siRNA with H101 oncolytic adenovirus." (PMID 23071601, 2012).
tumor (continued). "In an earlier report we found that down-regulation of Notch-1 decreased cell invasion, whereas Notch-1 overexpression by cDNA transfection led to increased tumor cell invasion." (PMID 22479394, 2012). "In nude mice bearing xenograft tumors derived from HeLa-S3 cells, the combination of H101/Notch1-siRNA therapies inhibited tumor growth." (PMID 23071601, 2012). "For example, Notch1, a member of Notch family receptor has been indicated as an oncogene in multiple tumor types." (PMID 22539939, 2012). "It should be noted that the PDX-1-Cre;Notch1lox/lox mice have Notch1 deleted from all pancreatic epithelial cells; however, other cells located in the tumor microenvironment, such as endothelial cells and immune cells, retain Notch1 expression." (PMID 23284900, 2012). "We found that eIF6 transcription is under the control of the transmembrane receptor Notch-1, a protein involved in a wide variety of human neoplasms, as well as in embryonic development and cell differentiation." (PMID 22348144, 2012). "To further investigate the mechanism of Notch1 mediated tumor suppression in pancreatic tumorigenesis we examined the effect of Notch1 deletion on acinar-to-ductal metaplasia both in vitro and in vivo." (PMID 23284900, 2012). "As expected, the growth ability was significantly enhanced after transfection indicating that elevated proliferation by Notch1 was indeed a pivotal element of metastasis in early stage tumor." (PMID 22506064, 2012). "Previous studies have demonstrated that Notch1 functions as a tumor suppressor gene in the skin by mechanisms impacting the tumor microenvironment." (PMID 23284900, 2012). "Although Notch1 was originally identified as an oncogene, recent evidence indicates the Notch proteins also function as tumor suppressors in a tissue-specific manner." (PMID 23284900, 2012). "Immunostaining of serial sections revealed co-localization of c-Src and Notch-1 immunoreactivities in the xenograft tumor tissue, implying a positive correlation between c-Src and Notch-1 activation in individual tumor cells." (PMID 22479394, 2012). "It has been reported that targeted knockdown of Notch1 gene expression by a small interfering RNA inhibits the invasion of tumor growth and enhances apoptosis in a variety of tumor cells." (PMID 22937170, 2012). "In order to verify our postulation, we transfected tumor cell lines with Notch1 plasmid and examined the alteration of tumor cell proliferation." (PMID 22506064, 2012). "In our study, HIF1A, similarly to NOTCH1, correlated with most of the other tumor markers but less with MUC1 or NKX2-1 as markers of lung physiology." (PMID 23028920, 2012). "To confirm that NOTCH1 signaling is impaired in regressing tumors, we isolated RNA from tumor-bearing mice left untreated or treated with doxycycline." (PMID 22992387, 2012). "Notch1 signaling in sporadic colon cancer induces adenoma formation in animal models whereas studies have found a protective role against tumor formation in colitis-an effect theorized attributed to its inflamed environment." (PMID 24696788, 2012). "These experiments aimed to identify a cell autonomous mechanism of Notch1 mediated tumor suppression." (PMID 23284900, 2012). "As compared with the PBS control group, the Notch1-siRNA or H101 monotherapy showed similar inhibition of tumor growth." (PMID 23071601, 2012). "Similar to Notch1, forced expression of Jagged1 also stimulated the proliferation and migration of tumor cells." (PMID 22506064, 2012).
tumor (continued). "The expression of Notch1 and Jagged1 were analyzed in tumor tissues and matched normal adjacent tissues obtained from 51 ccRCC patients." (PMID 22506064, 2012). "Expression of human N1C in pre-tumor thymocytes from the ROSA26 locus activated transcription of its known downstream targets such as endogenous Notch1, Hes1, Deltex1, c-myc and Notch3." (PMID 22393458, 2012). "Some miRNAs are capable of potentiating tumorigenic activity of oncogenes, such as Myc and Notch1, possibly by repressing known tumor suppressors." (PMID 22916024, 2012). "At the same time, Notch1 siRNA targets both the Notch-pathway mutated tumors and the minority CSC population of the tumor." (PMID 23071601, 2012). "The combined action of Notch1 knockdown and H101 oncolysis significantly inhibited tumor growth in vitro, suggesting an additional effect of the combined tumor therapy." (PMID 23071601, 2012). "In tissues from inoperable locally advanced and metastatic tumours, nuclear expression of Notch1, -3, -4, HES-1, and HEY-1 (all p≤0.001) was significantly increased compared to expression in resected tumours." (PMID 23226563, 2012). "In tumor cells treated by the combined Notch1-siRNA and H101, we found an enhanced induction of apoptosis in HeLa-S3 cells, but we did not detect significant alteration of caspase-3 or activated caspase-3 expression." (PMID 23071601, 2012). "Results from a flurry of recent studies confirmed that targeting DLL4/NOTCH1 signaling has a profound impact on tumor angiogenesis and growth." (PMID 21824400, 2011). "Additional Notch receptor-specific reagents or new conditional genetic mouse models will be instrumental for delineating the relative contribution of Notch1 and Notch4 to tumor angiogenesis." (PMID 21923938, 2011). "Recently generated Notch1-specific inhibitory antibodies exhibited tumor vessel effects similar to those seen following blockade to Dll4." (PMID 21923938, 2011). "On the other hand, it has also been reported that mutation of Notch1 can be an early or initiating event in T-ALL arising prenatally, to be complemented by a postnatal SIL-TAL1 fusion gene and emergence of tumor clones." (PMID 22128846, 2011). "Strong expression of NF-κB, but weak expression of Notch1, was observed in tumor tissues with lymph nodes involvement (P < 0.05 for both)." (PMID 21939555, 2011). "Administration of NP-siDCAMKL-1 into HCT116 xenografts resulted in tumor growth arrest, downregulation of proto-oncogene c-Myc and Notch-1 via let-7a and miR-144 miRNA-dependent mechanisms, respectively." (PMID 21929751, 2011). "We observed a significant reduction in Notch-1 mRNA in tumor xenografts treated with NP-siDCAMKL-1, DAPT, and NP-siDCAMKL-1+DAPT compared to NPs alone (control) or NP-siSCR treated tumors." (PMID 21929751, 2011). "Our aim was to investigate the contribution of NF-κB and Notch1 signaling to lymph node involvement and tumor-induced lymphangiogenesis in ESCC." (PMID 21939555, 2011). "Lastly, DAPT-mediated inhibition of Notch-1 resulted in HCT116 tumor growth arrest and down regulation of Notch-1 via a miR-144 dependent mechanism." (PMID 21929751, 2011). "While significant safety concerns have been raised in recent preclinical studies, the full therapeutic potential of targeting DLL4/NOTCH1 should be further explored given its remarkable impact on the tumor vasculature and tumor growth in preclinical models." (PMID 21824400, 2011). "NP-based-DCAMKL-1 knockdown in HCT116 tumor xenografts resulted in a marked decrease in Notch-1 mRNA (50%), which contains a putative predicted binding site for miR-144 in the 3'UTR." (PMID 21929751, 2011).
tumor (continued). "Given the potential roles of Notch signaling in adult stem cell regulation and tumorigenesis, we determined the effect of NP-siRNA-mediated knockdown of DCAMKL-1 on Notch-1 expression in HCT116 cell tumor xenografts." (PMID 21929751, 2011). "In tumors targeted by DLL4/NOTCH1 inhibition, the hyperproliferative state of endothelial cells, together with the reduced protection of the tumor endothelium by supporting cells, may render the tumor vasculature more susceptible to agents that selectively target proliferating cells." (PMID 21824400, 2011). "As phenotypically both Notch and RhoC signalling molecules regulate similar features during tumour progression, we explore the possibility of RhoC being a downstream effector of Notch1." (PMID 19953094, 2010). "Both classes of antibodies are selective for Notch1, bind Notch1 on the surface of human tumor cell lines, and inhibit ligand-induced expression of Notch target genes in cell lines expressing wild-type Notch1 receptors." (PMID 20161710, 2010). "This is of likely functional significance as, even in the presence of Notch2, deletion of the Notch1 gene is by itself sufficient to promote keratinocyte tumor development." (PMID 20442780, 2010). "Xenografts of MCF-7 and T47D Msi1 KD cells resulted in a marked reduction of tumor growth, reduced Msi1 and Notch1 expression and increased p21CIP1 expression." (PMID 20727204, 2010). "In this study, we show that RhoC regulates EMT during tumour progression in a manner similar to Notch1." (PMID 19953094, 2010). "Consistent with previous studies, Notch1 is present throughout all skin layers including the tumor-prone basal layer of the skin, whereas Notch2 is expressed exclusively in suprabasal keratinocytes." (PMID 21042537, 2010). "Considering that both Notch1 and RhoC regulate similar features during tumour progression, we explored the possibility of cross-talk between Notch1 and RhoC." (PMID 19953094, 2010). "Although there is data supporting the role of Notch1 in tumour progression, there is paucity of evidence of factors downstream of it that regulate these processes." (PMID 19953094, 2010). "Notch1 has been shown to exert regulations on tumour growth, invasion, metastasis and angiogenesis in various carcinomas." (PMID 19953094, 2010). "Recent evidence suggest that Notch1 enhances vertical growth phase by the activation of the MAPK and AKT pathways; inhibition of either the MAPK or PI3K-AKT pathway reverses the tumor cell growth induced by Notch1 signaling." (PMID 19828018, 2009). "The anti-tumor effect of Notch1 in murine skin appears to be mediated by p21Waf1/Cipinduction and repression of WNT signaling." (PMID 19828018, 2009). "In our studies, SBHA and VPA treatment of MTC tumor cells resulted in dose-dependent induction of the Notch1-intracellular domain, the active form of the protein." (PMID 20069043, 2009). "By contrast, consistent with the finding that Notch signalling promotes epidermal terminal differentiation, Notch1 acts as a tumour suppressor in the skin." (PMID 18342499, 2008). "Notch1 deletion also increases the sensitivity of the epidermis to developing tumours in response to activated Ras [33,34••]." (PMID 18342499, 2008). "In colon CSCs, quercetin combined with radiotherapy can reduce the levels of Jagged1 protein, γ-secretase complex components, and cleaved Notch1, upregulate miR-200b-3p, inhibit Notch signaling, change the division pattern of CSCs, and impair tumor regeneration." (PMID 41602823, 2026). "LIFUS-activated GVs remodel the tumor microenvironment by reducing cancer-associated fibroblast (CAF) abundance, decompressing the matrix, and selectively disrupting CAF-CD8+ T cell communication via a mechanosensitive Notch1-Jagged1 axis." (PMID 41806839, 2026).